NTN4 (netrin 4)
Diseases named in the same sentence as NTN4 in open-access papers (continued):
Sharing a sentence is not in itself a finding about the gene and the disease.
tumor (continued). "Alternatively, one study has reported that exogenous EGF can stimulate the expression of NTN4, a regulator of GBM tumor progression/proliferation via ITGB4-Akt signal activation." (PMID 36316307, 2022). "Thus, NTN4 could be acting both in autocrine and paracrine fashion in the tumor niche." (PMID 30160193, 2019). "In order to correlate patient’s disease staging with our NTN4 immunohistochemistry analysis, we organized the results in relation to PCNA expression levels, age, tumor stage, patient status, gender and primary tumor sites." (PMID 30160193, 2019). "Thus, Netrin-4 induced mural cell recruitment may play a role in the inhibition of tumor growth." (PMID 24472220, 2014). "To clarify the mechanisms by which Netrin-4 inhibits angiogenesis and reduces tumor growth, we examined the effects of Netrin-4 on VSMC in vitro and on tumor angiogenesis." (PMID 24472220, 2014). "NTN4 also plays a multifactorial role in various non-neuronal cells, such as endothelial cells, tumor cells, and stromal cells." (PMID 40136644, 2025). "Furthermore, EGF increases the expression of Netrin-4 in the U251MG cell line and prevents tumor cell senescence induced by DNA damage in GBM, hence it is regarded as a protective factor." (PMID 37208656, 2023). "NTN4 was significantly positively related to infiltration of CD8+ T cells, macrophages and neutrophils, whereas significantly negatively related to B cells and tumor purity." (PMID 35732855, 2022). "In base-like subtype, NTN4 expression was not related to tumor purity (r = − 0.168, P = 5.71e−02), whereas related to macrophages only (r = 0.201, P = 2.38e−02)." (PMID 35732855, 2022). "This correlation between netrin-4 expression levels, tissue stiffness and tumour invasion does not preclude netrin-4 also acting through an alternative mechanism independently or in addition to its biophysical role." (PMID 36355367, 2022). "Another intriguing result is that no NTN4 expression was found in tumor cells or stroma of patient’s whose primary tumor location was ascribed at the thoracic level." (PMID 30160193, 2019). "Among them were known cancer/testis antigen genes (PNMA5, SPATA22, ROR1, and CT45A6) and some new candidates (PAX2, HES4, PEG10, NTN4, PDE10A, and POSTN), these genes could be useful tumor markers and potential therapeutic targets." (PMID 30922328, 2019). "To determine whether NTN4 acts as a survival factor specifically through NEO1 or as a general survival factor, we overexpressed TrkC, a dependence receptor that acts as a tumor suppressor in NB and repeated TUNEL assays." (PMID 28038459, 2017). "Repression of NTN4 and HYAL1 may promote cell migration and invasive growth, whereas BAI3, VWF, and EPB41L4B probably participate in angiogenesis, attachment of tumor cells to endothelial surfaces, or reflect vascular structures in the tumors." (PMID 17054779, 2006). "Interestingly, NTN4 was intensely expressed in the endothelium throughout all the samples analyzed, independent of the tumor stage." (PMID 30160193, 2019). "In addition to the central nervous system, NTN4 is broadly expressed in non-neural cells, and regulates tissue development and tumor progression by modulating various cellular functions." (PMID 30514230, 2018). "FLRT3 is most strongly co-expressed with tumor suppressor gene TP63 and angiogenesis regulator gene NTN4 (Pearson correlation r = 0.83) (CBioportal), which suggests possible mechanisms by which HNF1B could exert the effects observed here – a control switch preventing EMT in non-tumor tissue." (PMID 27732966, 2016).
cancer (24 papers, 2012 to 2025). A tumor composed of atypical neoplastic, often pleomorphic cells that invade other tissues. "Reporter luciferase assays showed that MiR-210 mimics suppressed NTN4 3’ untranslated region-driven luciferase activity in cancer cells, but this effect was blocked after mutating miR-210 binding site." (PMID 38175202, 2024). "E59K, one of the hotspot mutations of NTN4, was detected in four patients with three cancers (READ, COAD, and UCEC) and both VEST3 and REVEL algorithms indicated this change was dual-damaging." (PMID 32251318, 2020). "Together, these data suggested that secreted NTN4, which is the ligand of integrin β1, enhances cancer stemness by regulating integrin β1 signaling." (PMID 38164180, 2024). "Increased miR-210 expression promoted migration ability of cancer cells by inhibiting NTN4 expression." (PMID 38175202, 2024). "Both mRNA and protein levels of NTN4 were much lower in cancer cells after coculture than in cancer cell monocultures." (PMID 38175202, 2024). "Narrowing the scope to cancer, NTN4 has been found to be involved in the development and metastasizing of several kinds of cancer." (PMID 30923634, 2019). "Based on our results, we propose that NEO1 and/or NTN4 are promising targets for use anti-cancer therapies, in particular to inhibit the tumoral metastasis." (PMID 28038459, 2017). "NTN4, an epigenetically regulated gene, plays a dual role in cancer metastasis." (PMID 41235257, 2025). "Anti-miR-210 increased NTN4 expression, while miR-210 mimics downregulated NTN4 in cancer cells." (PMID 38175202, 2024). "The spheroid formation capability of EXOSC5-depleted EC cells treated with rhNTN4 was analyzed to examine whether EXOSC5 promotes cancer stemness through secreted NTN4." (PMID 38164180, 2024). "Therefore, NTN4 was involved in cancer, but the exact role of NTN4 appeared to be dependent on the cancer type." (PMID 38546656, 2024). "Recently, increasing evidence has suggested that NTN4 plays a suppressor role in cancer." (PMID 38175202, 2024). "To verify whether NTN4 expression regulated by miR-210, we manipulated the expression of miR-210 in cancer cells by transient transfection with the miR-210 hairpin inhibitors or artificial miR-210 mimics." (PMID 38175202, 2024). "Overall, the results showed that EXOSC5 maintains cancer stemness via regulation of NTN4 secretion." (PMID 38164180, 2024). "Moreover, the majority of the data on NTN4 expression in various cancers have been demonstrated in experimental models, and its role and clinical significance in human malignancies remain uncertain." (PMID 37736464, 2023). "NTN4 may participate in the development and progression of a variety of cancers, NTN4 was proposed to serve as a prognostic biomarker for breast cancer." (PMID 35732855, 2022). "Additionally, eQTLs affect the expression of NTN4 in HNSC, KIRC, LAML, LGG, LUAD, PCPG, SKCM, and other cancers, including 5 eQTL that are associated with GWAS in LUAD." (PMID 32251318, 2020). "The variable expression patterns of NTN4 in different cancers could depend on many factors including the receptors available on the responsive cells, multiple signaling pathways activated and the concentration of protein." (PMID 27172792, 2016). "In cancers, the expression and functional role of NTN4 has been controversial." (PMID 27172792, 2016). "Emerging evidences have indicated that Ntn4 may play an important role in the development of multiple types of cancer." (PMID 25909166, 2015). "Furthermore, there's no investigation focusing on the value of Ntn4 as a serum biomarker for cancer diagnosis and prognosis, and the Ntn4 expression in GC patients and its correlation with the clinical features are still undetermined." (PMID 25909166, 2015). "Interestingly, NTN4 has been observed to serve as a bi-functional modulator in the angiogenic process, exhibiting both pro- and anti-angiogenic activity that differs according to the type of cancer." (PMID 37736464, 2023).
cancer (continued). "It differs per cancer type whether NTN4 has a positive or negative association with disease progression." (PMID 30923634, 2019). "EXOSC5 upregulates NTN4 expression, activating c-MYC through the integrin β1/FAK/SRC pathway to sustain cancer stem cell activity." (PMID 41235257, 2025). "Therefore, NTN4 may serve as a regulator of integrin signaling in cancer progression." (PMID 38164180, 2024). "It is worth noting that the mutations and potential mirRNA targeting of NTNG1 and NTNG2 in cancer exhibit rates that are much higher than those predicted for NTN1 and NTN4." (PMID 32251318, 2020). "NEO1 and NTN4 are expressed in sites where NB originates, such as in the DRG of the embryonic neural crest, and we hypothesize that their functions persist throughout cancer progression, as a result of an impairment in the normal developmental signaling." (PMID 28038459, 2017).
retinopathy (1 paper, 2016). "Therefore, we undertook an analysis of the role of netrin-4 in pathological blood vessel formation using an oxygen induced retinopathy (OIR) mouse model." (PMID 26732856, 2016).
NTN4 also shares sentences with these, for which no sentence is quoted: acute myeloid leukemia (1 paper); bladder cancer (1); brain tumor (1); breast adenocarcinoma (1); cervical intraepithelial neoplasia (1); choroidal neovascularization (1); Cognitive impairment (1); colorectal tumors (1); cutaneous melanoma (1); diabetic retinopathy (1); hearing loss (1); hypertrophy (1); intrauterine growth restriction (1); kidney cancer (1); lung carcinoma (1); medullary thyroid cancer (1); medulloblastoma (1); metastatic tumors (1); multiple sclerosis (1); osteosarcoma (1); pancreatic cancer (1); prostate tumors (1); renal carcinoma (1); Stroke (1); uveal melanoma (1).